IL17A (interleukin 17A)
Diseases named in the same sentence as IL17A in open-access papers (continued):
Sharing a sentence is not in itself a finding about the gene and the disease.
colon polyp (4 papers, 2023 to 2024). "Moreover, both populations observed a strong correlation between the colon polyp number and IL-17A cytokines." (PMID 39513912, 2024). "Interestingly, the colon polyps (LIP) in the AOM-DSS treated Gpr15-KO mice showed distinct (e.g., increased MDSCs) as well as shared (e.g., increased IL-17A+ CD4+ and IL-17A+ CD8+ T cells) immune features of human CRC with reduced GPR15 expression." (PMID 38074634, 2023).
conjunctivitis (4 papers, 2020 to 2026). Inflammation of the conjunctiva of the eye. "Regarding Th17/Th22 responses, IL-17A and IL-22 mRNA expression levels increased in the right eye, which had more severe conjunctivitis, than in the left." (PMID 40861543, 2025). "In addition, the mRNA expression of IL-17A was increased in the right eye with severe conjunctivitis." (PMID 40861543, 2025). "Both IL-22 and IL-17A may be involved in the pathophysiology, but the clinical findings and pathology of IL-22 and IL-17A-associated conjunctivitis have not been fully elucidated and require further research." (PMID 40861543, 2025).
corneal disease (4 papers, 2012 to 2022). "Further, in support of the contribution of IL-17A in the corneal disease that develops in the nude recipients, we measured the number of IL-17A, CCL20, MMP-3 and MMP-9 mRNA transcripts in this tissue." (PMID 22590618, 2012). "In this study, we evaluated the cytokine profiles of IL-2, IFN-γ, ICAM-1, IL-5, IL-6, IL-8, IL-10, IL-1β, MCP-1, IL-17A, IP-10, G-CSF, and VEGF-A in the AqH of BK patients before and after DMEK and in a control group without corneal disease." (PMID 34426617, 2021).
Cryptococcal meningitis (4 papers, 2019 to 2025). Meningeal inflammation produced by cryptococcus neoformans, an encapsulated yeast that tends to infect individuals with acquired immunodeficiency syndrome and other immunocompromised states. "18-week survival after diagnosis of cryptococcal meningitis was associated with higher CSF leukocytes at baseline with greater T helper 1 (IFN-γ, IL-2 and TNF-α cytokines), T helper 17 (IL-17A cytokine) and CXCR3+ T cell (CXCL10 chemokine) responses." (PMID 39928682, 2025). "In plasma, IL-12 p40, IL-17A, and VEGF contributed strongly to the PC that was statistically significantly associated with high baseline fungal burden—an established predictor of mortality in cryptococcal meningitis." (PMID 40271162, 2025). "Notably, as with mice, IL-17A is induced in human patients with cryptococcal meningitis." (PMID 31329596, 2019). "Given the positive correlation association of the CSF leukocytes and measured CSF protein and cytokine levels, the CSF leukocytes and other neuroimmune activated cells are the likely source of immune modulating IL-17A and Th1 cytokine; TNF-α cytokine factors in CSF with cryptococcal meningitis." (PMID 39928682, 2025).
cutaneous melanoma (4 papers, 2021 to 2026). A primary melanoma arising from atypical melanocytes in the skin. "First, we examined the effects of an IL-17A-neutralizing antibody (α-IL-17A) and recombinant mouse IL-17A (rm-IL-17A) on tumor growth kinetics in the ICI-sensitive MT/ret-derived primary cutaneous melanoma (CM) mouse model (human ret transgene, BRAF-WT20)." (PMID 37525015, 2023).
dacryoadenitis (4 papers, 2015 to 2025). Inflammation and enlargement of the lacrimal gland. "Our results showed that deletion of IL-17A in the CD25KO model accelerated onset and severity of dacryoadenitis." (PMID 25889094, 2015). "Our previous studies showed that CD25KO mice have increased expression of both IL-17A and IFN-γ transcripts in LG tissue and that deletion of IFN-γ delayed the onset and severity of dacryoadenitis in this strain." (PMID 25889094, 2015). "We wish to emphasize that this is the first report of using a combination several DKOs and one TKO in an attempt to dissect individual contributions of IL-17A and IFN-γ in dacryoadenitis in a murine model." (PMID 25889094, 2015).
dental caries (4 papers, 2014 to 2025). The decay of a tooth, in which it becomes softened, discolored, and/or porous. "Keeping this in mind, the present study evaluated the association of salivary Vitamin D levels and the levels of LL-37, IL-6, and IL-17A in the severity of dental caries." (PMID 38218769, 2024). "Among them, only IL-10 and IL-17A showed a significantly higher level in the group of children with dentofacial tissue inflammation compared to the group with uncomplicated dental caries." (PMID 39201367, 2024).
enteropathy (4 papers, 2016 to 2022). "Numerous cytokines that circulate at very low concentrations were not able to be quantified in the cohort and several of these (amylin, glucagon, interferon-γ, IL-1B, IL-17A) have direct associations with MetS, which may undercut the argument for enteropathy as an etiology for MetS." (PMID 36096405, 2022). "It is possible that an IFN-γ-driven chronic, sub-clinical enteropathy which facilitates tumorigenesis is reversed or alleviated by IL-17A production." (PMID 33674735, 2021). "A therapeutic strategy targeting IL-17A could be a treatment option for such enteropathy." (PMID 31727909, 2019).
Fever (4 papers, 2019 to 2023). Body temperature elevated above the normal range. "In the current study, there was some elevation of IL‐17A in the High MP‐DNA MPP, Fever MPP, and Severe MPP groups, but this elevation was not statistically different, possibly due to the small sample size." (PMID 37249293, 2023).
hemorrhage (4 papers, 2017 to 2023). Loss of blood from the vascular compartment to the exterior or into nonvascular body space as a result of rupture or severance of the blood vessels. "We summarized that SNPs of five inflammatory genes (IL6, APOE, IL1B, IL17A, MMP9) were reported to be associated with bAVM-related hemorrhage." (PMID 37065486, 2023). "Twelve single nucleotide polymorphisms (SNPs), including IL6 rs1800795, IL17A rs2275913, MMP9 rs9509, VEGFA rs1547651, and EPHB4 rs314353, rs314308, and rs314313, were associated with bAVM-related hemorrhage." (PMID 37065486, 2023). "This led to the identification of statistically significant association between bAVM-related hemorrhage and twelve heritable variants of seven genes (IL6, APOE, IL1B, IL17A, MMP9, EPHB4, and VEGFA) involved in the inflammatory and angiogenic signaling pathways." (PMID 37065486, 2023). "IL-17 has also been identified to predict organ damage through computational network analysis of systemic inflammatory markers in blunt injury patients and neutralizing IL-17A attenuated organ damage in a trauma/hemorrhage mouse model." (PMID 30319602, 2018).
hypothyroid (4 papers, 2020 to 2025). "Consistently with our results, serum IL-17A has been inversely associated with serum TSH in hypothyroid HT." (PMID 32477272, 2020). "However, we will verify whether different IL-17A levels have diverse side effects on pregnancy outcome in animals with hypothyroidism in the future." (PMID 32477272, 2020). "Therefore, we speculated that when the TSH level was elevated in HT patients with hypothyroidism, it would counteract the effect of increasing IL-17A levels accompanied by TGAb production." (PMID 32477272, 2020).
Klebsiella pneumonia (4 papers, 2017 to 2023). An pneumonia caused by infection with Klebsiella. "In fact, a previous report noted that a significant fraction of lung CD4+IL17+ TRM cells were derived from IL-17A-producing effector (Th17) cells following immunization with heat-killed Klebsiella pneumonia." (PMID 38093320, 2023). "IL-17A expressing immune cells, such as Th17 cells, are involved in the elimination of extracellular lung pathogens, such as Streptococcus pneumoniae and Klebsiella pneumonia." (PMID 33411748, 2021).
Large vessel vasculitis (4 papers, 2013 to 2024). A type of vasculitis (inflammation of blood vessel walls) affecting large arteries such as the aorta and branches of the aorta. "To conclude, our finding of increased Th17 cells and serum IL-17A and IL-23 in TA offers newer insights into the pathogenesis of a rare large vessel vasculitis." (PMID 27034824, 2016). "In their study, mice deficient in interferon regulatory factor-4, a protein that inhibits IL-17A production, rapidly developed large-vessel vasculitis and showed increased IL-21 synthesis in addition to increased IL-17A production." (PMID 23799890, 2013).
lymphedema (4 papers, 2009 to 2024). Excess fluid collection in tissues, causing swelling. "Babu and colleagues reported that Th17-associated cytokines like IL-17A were increased in PBMCs from patients with lymphedema upon Brugia malayi antigen stimulation." (PMID 29931394, 2018). "IFN-γ levels in CD4+PD-1+ T cells and IL-17A levels in CD4+ T cells were downregulated in post-LVA compared with lymphedema." (PMID 37250774, 2023). "The inflammatory cytokines IFN-γ, IL-4, and IL-17A have been reported to negatively control the formation of lymphatic vessels involved in the progression of lymphedema." (PMID 37250774, 2023). "To address the role of Th17 cells in filarial lymphedema, we examined the expression of IL-17A, IL-17F, IL-21 and IL-22 as well as the upstream inducing cytokines IL-23, IL-6 and IL-1β in PBMCs of lymphedema patients following BmA or PPD stimulation." (PMID 19381284, 2009). "In our study, we found augmented induction of IL-17A, IL-17F, IL-21, and IL-23 in patients with filaria-induced lymphedema." (PMID 19381284, 2009). "Babu and collaborators demonstrated that the expression of the Th17 cytokines IL-17A, IL-17F, IL-21, and IL-23 was significantly upregulated in filaria-infected patients with lymphedema, suggesting a role for Th17 cells in the pathogenesis of filaria-induced pathology." (PMID 38587077, 2024). "The upregulation of the exhaustion marker, IFN-γ, and IL-17A and downregulation of the TCR repertoire diversity in patients with lymphedema compared with post-LVA and HCs can be associated with immune dysfunction and progression of lymphedema." (PMID 37250774, 2023). "Most effector cytokines known to be produced by Th17 cells—IL-17A, IL-17F, and IL-21 (with the exception of IL-22)—are induced at significantly higher levels in patients with lymphedema, suggesting an important role for these cytokines in development of this disease process." (PMID 19381284, 2009). "Notably, expression of the Th17 family of cytokines—IL-17A, IL-17F, IL-21, and IL-23—was also significantly upregulated by BmA stimulation in lymphedema patients." (PMID 19381284, 2009). "To understand the correlation between cytokine production by T cells and lymphedema, we compared the expression of IFN-γ, IL-4, and IL-17A on CD4+ and CD8+ T cells in lymphedema, post-LVA, and HCs." (PMID 37250774, 2023). "We examined the inflammatory cytokine production in CD4+ T cells between lymphedema and post-LVA and found that IFN-γ in CD4+PD-1+ T cells and IL-17A in CD4+ T cells were downregulated post-LVA compared with that in lymphedema, while IL-4 in CD4+ T cells was not significantly different." (PMID 37250774, 2023). "IL-17A production in CD4+, CD4+PD-1+, and CD4+PD-1- cells was downregulated in post-LVA compared to that in lymphedema (2.7 [1.8–3.3] vs. 1.6 [0.9–2.3], p = 0.01; 5.5 [3.6–6.3] vs. 4.0 [2.7–4.5], p = 0.04; and 1.3 [0.8–2.5] vs. 0.8 [0.4–1.6], p = 0.01, respectively)." (PMID 37250774, 2023).
macrophage activation syndrome (4 papers, 2016 to 2024). A complication of rheumatic disease that is caused by excessive activation and uncontrolled proliferation of T lymphocytes and well-differentiated macrophages. "Nevertheless, they reported that the overexpression of IL-17A separated both MIS-C and KD from secondary Hemophagocytic Lymphohistiocytosis (sHLH)/Macrophage Activation Syndrome (MAS)." (PMID 39457139, 2024).
microcephaly (4 papers, 2019 to 2023). A congenital or acquired developmental disorder in which the circumference of the head is smaller than normal for the person's age and sex. "In a study investigating the mechanisms of cell damage in the central nervous system of fatal cases with microcephaly caused by Zika virus, increased expression levels of both IL-17A and IL-23 were observed, as well as enhanced Th1–mediated inflammation." (PMID 35805137, 2022). "Unsupervised hierarchical cluster analysis demonstrated that ZIKV-exposed individuals with microcephaly exhibited a tendency of increased levels of pro-inflammatory mediators in CSF, as IL-1β, IL-12p70, IL-15, IL-17A, IFN-γ, and MIP-1α (CCL3) compared to controls." (PMID 33875756, 2021). "In ZIKV-exposed neonates without microcephaly, GMCSF is the top node, also with only positive interactions, followed by pro-inflammatory cytokines such as IL-1RA, IL-12p70, IL-17A, TNF-α and IFN-α." (PMID 33875756, 2021).
mycosis fungoides (4 papers, 2020 to 2024). Classical mycosis fungoides is the most common type of mycosis fungoides (MF), a form of cutaneous T-cell lymphoma, and is characterized by slow progression from patches to more infiltrated plaques and eventually to tumors. "The authors speculated whether low levels of IL-17A and IL-17F in mycosis fungoides may be connected to impaired immune surveillance, thereby facilitating tumorigenesis." (PMID 38607023, 2024).
non-proliferative diabetic retinopathy (4 papers, 2020 to 2023). Early stage diabetic retinopathy, characterized by the absence of neovascularisation of the retina. "Previously, we determined that Interleukin (IL)-17A plays a pivotal role in the onset and progression of non-proliferative diabetic retinopathy in diabetic mice." (PMID 36675261, 2023). "We and others previously provided evidence that Interleukin-17A (IL-17A) plays a pivotal role in non-proliferative diabetic retinopathy." (PMID 36674854, 2023). "Recently, we established a pathological role for IL-17A in the onset of non-proliferative diabetic retinopathy in Streptozotocin (STZ)-induced diabetic mice." (PMID 32429598, 2020). "Hence, we identified IL-17A as a potential therapeutic target for early-stage non-proliferative diabetic retinopathy." (PMID 36675261, 2023). "Hence, weekly 50 μg/mL anti-IL-17A treatments can halt the retinal pathogenesis and vascular impairment that is observed in early stage non-proliferative diabetic retinopathy." (PMID 36674854, 2023). "Further suggesting that anti-IL-17A could be a potentially novel therapeutic for non-proliferative diabetic retinopathy." (PMID 36674854, 2023). "Further, in diabetic mice it was determined that IL-17A played a pivotal role in BRB permeability, vascular impairment, and the onset of non-proliferative diabetic retinopathy." (PMID 32429598, 2020).
ocular infection (4 papers, 2016 to 2024). "Trigeminal ganglia (TG) from some WT and IL17A−/−, IL17RA−/−, IL17RC−/−, and IL17RA−/−RC−/− mice that survived ocular infection were isolated on day 28 PI." (PMID 32516406, 2020). "In our study we have shown the absence of CNS demyelination in IL-17A-/- mice following ocular infection with HSV-IL-2 virus, while transfer of T cells from WT mice to recipient IL-17A-/- mice caused CNS demyelination in infected mice." (PMID 36817487, 2023).
oral disease (4 papers, 2017 to 2021). "Among those cytokines, IL-17A is of paramount importance in the context of oral disease." (PMID 32560286, 2020).
otitis media with effusion (4 papers, 2019 to 2026). Otitis media associated with accumulation of fluid in the middle ear. "Here, we evaluated the expressions of IL-17A and associated genes in hypertrophic adenoid tissues of children with sleep-disordered breathing (SDB) and otitis media with effusion (OME) and their association with pneumococcal carriage." (PMID 31882693, 2019).
periapical granuloma (4 papers, 2016 to 2026). Chronic nonsuppurative inflammation of periapical tissue resulting from irritation following pulp disease or endodontic treatment. "Consistently, elevated IL17A expression has been detected in periapical granulomas and cysts, promoting neutrophil recruitment and osteoclast-mediated bone resorption." (PMID 41614937, 2026). "The expression of IL-17A was significantly upregulated in the periapical granuloma, radicular cyst, and periapical abscess in comparison with healthy controls (P < 0.0001)." (PMID 34539639, 2021). "Nuclear receptor transcription factors RXR/VDR and RORγt (which shares sequence similarity with RXR) may be involved in periapical granuloma, supported by substantial expression of IL-17A." (PMID 34539639, 2021). "On estimation of IL-21 levels in periapical granulomas, it was demonstrated that IL-21 along with IL-17A, TNF-α (tumour necrosis factor-α), and IFN-γ were higher in active periapical granulomas, while IL-4, IL-9, IL-10, and IL-22 were higher in inactive periapical granulomas." (PMID 26998377, 2016).
polymyositis (4 papers, 2017 to 2025). A rare idiopathic inflammatory myopathy characterized by symmetric proximal muscle weakness and elevated muscle enzymes. "However, the efficacy of TNF-α inhibitors in the treatment of polymyositis is uncertain and has only been reported on a case-by-case basis, with no reports on IL-17A inhibitors in the treatment of polymyositis." (PMID 40441209, 2025).
primary sclerosing cholangitis (4 papers, 2021 to 2024). "The pathogenesis of primary sclerosing cholangitis (PSC) is unclear, although studies implicate IL-17A as an inflammatory mediator in this disease." (PMID 37886596, 2023).
protozoal infections (4 papers, 2014 to 2021). "Although IL17A is known to be involved in the host response to protozoal infections, and its production has been associated with the protective response to coccidial infections, the specific effect of IL17A on E. tenella infection has not been clearly defined." (PMID 24571471, 2014). "The role of IL-17A in malaria infection, and thus an understanding of its potential role in vaccine-induced protective immunity, is still unclear; however, it has been shown to play a protective role in other protozoal infections (reviewed in reference 38)." (PMID 34663097, 2021). "Although these mechanisms have been proposed in different bacterial or protozoal infections, we cannot rule out that IL-17A might play a similar role during F. hepatica infection." (PMID 33193292, 2020).
pyoderma gangrenosum (4 papers, 2023 to 2025). An idiopathic, rapidly evolving, and severely debilitating disease occurring most commonly in association with chronic ulcerative colitis. "An obvious example is IL-17A rich wound fluid isolated from venous ulcers and lesional tissues of patients with pyoderma gangrenosum." (PMID 40491919, 2025).
rectal cancer (4 papers, 2020 to 2023). A primary or metastatic malignant neoplasm that affects the rectum. "Several Th17-type proteins including CCL20, IL-17A and IL-17A/F are secreted at higher levels from rectal cancer tissue compared to normal rectal tissue." (PMID 33540635, 2021).
scrub typhus (4 papers, 2011 to 2021). Scrub typhus is a rare dust mite-borne infectious disease caused by the Orientia tsutsugamushi bacterium and characterized clinically by an eruptive fever which is potentially serious. "However, IFN-γ+ or IL-17A+ MAIT cell levels were comparable between scrub typhus patients and HCs." (PMID 27463223, 2016).
seborrheic dermatitis (4 papers, 2020 to 2025). A chronic, inflammatory skin disorder that affects the scalp, central face and skin folds; it is characterized by scaling and itching. "Of note, an increased incidence of seborrheic dermatitis was reported as an adverse event accompanying administration of the anti-IL-17A antibody Ixekuzumab, and a genetic variant of IL23R was found associated with a decrease in dandruff." (PMID 32477963, 2020).